IL17C (interleukin 17C)
Diseases named in the same sentence as IL17C in open-access papers (continued):
Sharing a sentence is not in itself a finding about the gene and the disease.
Candidemia (1 paper, 2025). A form of invasive candidiasis where species of CANDIDA are present in the blood. "In contrast, IL-17C is markedly downregulated in isolated candidemia, potentially affecting clinical outcomes." (PMID 41229429, 2025). "Nonetheless, this three-protein inflammatory signature—LAP-TGF beta-1, TRANCE, and IL-17C—effectively differentiates critically ill patients with bacterial co-infection within the context of candidemia." (PMID 41229429, 2025). "In our study, the expression of the IL-17C protein varied between the two subgroups of candidemia, with a significant reduction in isolated candidemia." (PMID 41229429, 2025). "The IL-17 family consists of IL-17A to IL-17F; the roles of IL-17A and IL-17C cytokines have been of great interest in the context of candidemia." (PMID 41229429, 2025). "Bacterial infection triggers both IL-17A and IL-17C, whereas candidemia exhibits a contradictory pattern, upregulating IL-17A and downregulating IL-17C." (PMID 41229429, 2025). "Furthermore, the multiple-group comparison showed significant differences in LAP-TGF beta-1, TRANCE, and IL-17C expression among C, BC candidemia subgroups, and controls." (PMID 41229429, 2025). "Cases with isolated candidemia showed a significant upregulation of TRANCE (p=0.006) and LAP-TGF beta-1 (p=0.01), along with a notable downregulation of IL-17C (p=0.004)." (PMID 41229429, 2025). "Conversely, IL-17C alone (being downregulated in isolated candidemia) performed only moderately as a negative discriminator between C and BC." (PMID 41229429, 2025).
crescentic glomerulonephritis (1 paper, 2020). A histopathologic term for a pattern of diseases characterized by extensive crescent formation in the glomeruli; patients present clinically with rapid deterioration of renal function, and possible progression to end-stage renal failure within weeks or months. "In the nephrotoxic nephritis (NTN) mouse model for crescentic glomerulonephritis, we showed that Il17c is upregulated as early as 12 h after induction of the disease, while Il17a and Il17f expression starts after a couple of days." (PMID 32174926, 2020).
Crohn disease (1 paper, 2018). A gastrointestinal disorder characterized by chronic inflammation involving all layers of the intestinal wall, noncaseating granulomas affecting the intestinal wall and regional lymph nodes, and transmural fibrosis. "In patients with Crohn's disease, IL-36γ induces TNF-α expression in KCs and sustains a self-amplifying pro-inflammatory loop with IL-17C by inducing its own expression and IL-17C." (PMID 29416822, 2018).
cutaneous candidiasis (1 paper, 2015). Candidiasis of the skin manifested as eczema-like lesions of the interdigital spaces, perleche, or chronic paronychia. "In this study, we used the most widely accepted models of oral, dermal and cutaneous candidiasis, none of which revealed a role for IL-17C or IL-17RE in host defense." (PMID 25849644, 2015). "The similarities between WT littermate controls and IL-17RE-/- mice indicate that IL-17C signaling via IL-17RE is not essential for protection from or the resolution of cutaneous candidiasis, whereas IL-17A signaling through IL-17RA/IL-17RC is nonredundant." (PMID 25849644, 2015).
dementia (1 paper, 2023). Loss of intellectual abilities interfering with an individual's social and occupational functions. "Our findings highlight the upregulation of several functionally immune-related proteins in dementia, such as IL17D, IL17C, IL17RB, and IL1B, among which IL17D also showed a strong negative correlation with cognitive performance." (PMID 37175824, 2023).
differentiated thyroid carcinoma (1 paper, 2019). Differentiated thyroid carcinoma (DTC), also known as papillary or follicular thyroid carcinoma, is a slow-growing malignancy usually presenting in adults as an asymptomatic thyroid mass. "Moreover, IL17C overexpression was observed in differentiated thyroid cancer and associated with the recurrence and mortality." (PMID 30661062, 2019).
eosinophilia (1 paper, 2018). "Next, we investigated the role of IL-17C in development of airway eosinophilia induced by inhalation of papain, which is a papaya–derived cysteine and a homologue to house dust mite-derived Der p1 and human cathepsin B26." (PMID 30356086, 2018). "After papain inhalation, airway eosinophilia was assessed by the eosinophil count in BAL fluids and was similar in both Il17c−/− and wild-type mice." (PMID 30356086, 2018).
fibrosis (1 paper, 2014). the formation of excess fibrous connective tissue in an organ or tissue in a reparative or reactive process. "The frequency of IL-17A and IL-17F distinguish SSc to morphea individuals while dermal expression of IL-17C (low) and IL-17E (high) identifies a fibrosis-specific motif." (PMID 25136988, 2014).
follicular lymphoma (1 paper, 2022). Follicular lymphoma is a form of non-Hodgkin lymphoma characterized by a proliferation of B cells whose nodular structure of follicular architecture is preserved. "Among follicular lymphoma, a higher CTL level indicates better patient survival, but only when IL-17C has a high expression level (p < 0.05)." (PMID 36159856, 2022).
Giardia infections (1 paper, 2021). "First we studied cytokines that earlier have been shown to be up-regulated during Giardia infections in mice, i.e. IL-1, IL-2, IL-4, IL-5, IL-9, IL-10, IL-12, IL-17a, IL-17c, IFN-γ, TGF-β, and TNF-α." (PMID 34335577, 2021).
gonococcal infection (1 paper, 2024). "Because IL-17C treatment induced a similar pro-inflammatory response as gonococcal infection in human FTOC, we questioned whether morphological changes to the epithelium would also be similar." (PMID 38704381, 2024). "Even in untargeted studies of gonococcal infection, however, IL17C expression was not upregulated." (PMID 38704381, 2024).
intestinal tumors (1 paper, 2024). "Furthermore, in intestinal epithelial cells (IECs), microbiota in intestinal tumors up-regulates IL-17C through Toll-like receptor (TLR) -MyD88-dependent signaling, and microbiota-driven IL-17C induces Bcl-2 and Bcl-xL expression in IECs in an autocrine manner." (PMID 39906741, 2024).
melanoma (1 paper, 2022). A malignant, usually aggressive tumor composed of atypical, neoplastic melanocytes. "For melanoma, the expression of IL-17C was positively correlated with the CTL level (GSE22153: r = 0.357, p < 0.05)." (PMID 36159856, 2022).
mesothelioma (1 paper, 2025). A usually malignant and aggressive neoplasm of the mesothelium which is often associated with exposure to asbestos. "Expression of interleukins IL17C, IL23A and IL24 were greater in R- vs NR-mesotheliomas; Benajmini-Hochberg adjusted P values < 0.05." (PMID 40691143, 2025).
pelvic inflammatory disease (1 paper, 2024). Pelvic inflammatory disease (PID) is an acute or chronic inflammation in the pelvic cavity. "Since inflammation is a hallmark of symptomatic N. gonorrhoeae infection and inherent to pelvic inflammatory disease, we hypothesized that IL17C is involved in the promotion of inflammation by N. gonorrhoeae." (PMID 38704381, 2024).
tendinopathy (1 paper, 2025). "In addition, here, we demonstrate the differential expression of IL17A in contrast to the other IL-17 family members, IL17B, IL17C, IL17D and IL17E in early-stage tendinopathy compared with late-stage tendinopathy and healthy tendon." (PMID 39988349, 2025).
ulcerative colitis (1 paper, 2014). An inflammatory bowel disease involving the mucosal surface of the large intestine and rectum. "In ulcerative colitis (UC) 5 genes (CXCL14, CXCL5, GATA3, IL17C, and IL4R) were hypermethylated compared to healthy controls." (PMID 25526479, 2014).
vaginal candidiasis (1 paper, 2015). "Clearly, future studies to define the biological activities of IL-17C signaling in vaginal candidiasis are warranted." (PMID 25849644, 2015).
vitiligo (1 paper, 2024). Generalized well circumscribed patches of leukoderma that are generally distributed over symmetric body locations and is due to autoimmune destruction of melanocytes. "Notably, proteins such as IL-17C, CXCL10, NKR2B4 (CD244), and TNF receptor superfamily member 11b (TNFRSF11B) exhibited bidirectional causality with vitiligo." (PMID 38660673, 2024).
infection (34 papers, 2015 to 2025). The state of being infected such as from the introduction of a foreign agent such as serum, vaccine, antigenic substance or organism. "As delayed wound closure in IL-17C- and IL-17RE-deficient mice was already visible at 2 days post-infection, IL-17C/IL-17RE-mediated cell proliferation and differentiation is likely an early event in our model." (PMID 34576717, 2021). "Again, IL-17C-/- and IL-17RE-/- mice demonstrated the same susceptibility to disseminated disease as WT littermate controls, while IL-17RA-/- were reproducibly more susceptible to infection." (PMID 25849644, 2015). "The protein expression of three proteins (IL-17C, IL-18, and IL-10RB) was significantly decreased in caspase-1-deficient cells compared to Cas9 cells following HK1651 infection." (PMID 40137780, 2025). "Caspase-1- and caspase-4-deficient cells showed significantly altered cytokine and chemokine profiles after infection with A. actinomycetemcomitans, showing reduced IL-17C and IL-18 release." (PMID 40137780, 2025). "In conclusion, we identified a group of cytokines, including IL-17C, MMP-10, FGF-23, CCL23, FGF-19 and CXCL5 that are differentially regulated during asymptomatic and mild symptomatic infections and are known to be associated with tissue repair functions." (PMID 35479098, 2022). "Tissue culture studies also demonstrated that knockdown of IL-17C or its receptor IL-17RE in airway epithelial cells reduces the expression of inflammatory mediators including neutrophilic chemokines in response to infection." (PMID 33411748, 2021). "In contrast to other members of the IL-17 family of cytokines, IL-17C is upregulated early during infection, maintains integrity of the epithelial layer barrier, and mediates the innate immune response." (PMID 33162788, 2020). "During cumulative measurements, HRV-induced cytokines were allowed to accumulate in the apical and basolateral milieu for increasing time periods, and IL-17C protein levels in the basolateral medium appeared to peak around 48 h post infection." (PMID 32232015, 2020). "In mice IL17RE is the receptor for IL-17C, which has an essential role in host mucosal defense against infection and is critical for a successful immune response against bacterial infection." (PMID 32228433, 2020). "In summary, therefore, we demonstrate that apical infection of airway epithelial cells with HRV induces a vectorial basolateral IL-17C protein release, likely from both apical and basal HBE cells." (PMID 32232015, 2020). "This is consistent with the significant increase in TEER at 24 h post ETEC infection or IL-17C stimulation." (PMID 31221216, 2019). "As it was previously reported that IL-17C is preferentially expressed in IECs, we assessed if this IL-17C induction in the jejunum after C83901 infection also comes from the IECs." (PMID 31221216, 2019). "The effects of C83901 infection and IL-17C on occludin protein expression were further confirmed by an immunofluorescence assay and Western blotting." (PMID 31221216, 2019). "In the skin, similar to early responses of the gill, responses to infection unique to low density fish at 24 h (n = 1965) were enriched for increased expression of inflammatory pathways (e.g. il17c)." (PMID 30285628, 2018). "The protein expression of two proteins (IL-17C and IL-18) was significantly decreased and the protein expression of two proteins (TGF-α and LIF) was significantly increased in caspase-4-deficient cells compared to Cas9 cells following HK1651 infection." (PMID 40137780, 2025). "Additionally, IL-17C is an epithelial-derived cytokine that is involved in recruitment neutrophils with high NETosis activity and is expressed earlier in infection than other IL-17 cytokine family members." (PMID 41583494, 2025).
infection (continued). "Similar to the protein level, the administration of a high dose of GUANKE reduced the transcription of CCL2 (the gene encoding MCP-1), TNFA, and IL6 on the third day after infection, and decreased the transcription of CCL2, TNFA, IL1B, IL6, and IL17C on the fifth day after infection." (PMID 39431894, 2024). "For this experiment, infection with a piliated variant of N. gonorrhoeae was included as a treatment to ensure IL-17C was not secreted in response to something uniquely produced by bacteria during in vitro growth." (PMID 38704381, 2024). "Therefore, it is possible that changes in microbiota during symptomatic infection modulates systemic circulating levels of IL-17C." (PMID 35479098, 2022). "Similarly, but to a lesser extent, Il17c was significantly induced by infection (4.7-fold, p = 2.84E-01)." (PMID 36704785, 2022). "In addition, knockdown of IL-17C in cultured bronchial epithelial cells reduced the induction of chemokines in response to infection and neutrophil chemotaxis." (PMID 33411748, 2021). "Expression of IL17re/IL17C is important in mucosal immunity against bacterial pathogens such as Citrobacter, and this cytokine previously reported to be upregulated in response to infection by a variety organism, including viruses, fungi, and bacteria." (PMID 33897648, 2021). "In the later course of infection, IL-17A (which shares the receptor IL-17RA with IL-17C) released from immune cells such as γδ T cell may compensate the loss of IL-17C-signaling in S. aureus-infected wounds." (PMID 34576717, 2021). "il17c, which displayed a 20-fold upregulation during infection of untreated HIBCPP cells with the Nm capsule-deficient mutant, was upregulated 191-fold by the bacteria when the Erk1/2 signalling pathway was inhibited during infection." (PMID 34863201, 2021). "After this point, high IL-17C levels were consistently measured up to 120 h post-infection." (PMID 32232015, 2020). "Recent studies demonstrate that IL-17C plays a key role in regulating the innate immune function of epithelial cells and acts as a link between inflammation and maintenance of the mucosal barrier function during infection." (PMID 33162788, 2020). "A potential direct effect of a viral gene could be mediated by HSV-2-infected cell protein 0, since this protein induces IL-17c expression during infection of human keratinocytes." (PMID 32669337, 2020). "The different impact of HSV-2 MS or 333 infection on neurite outgrowth may have been due to strain-specific effects on the expression or activity of IL-17c or AGMs." (PMID 32669337, 2020). "Another important cytokine produced by epithelial cells in response to infection is IL-17C." (PMID 26426272, 2015). "An increased circulating concentration of IL-17C was detected both in the discovery and independent cohort, both at the time of diagnosis and in samples 10 days before the diagnosis of IA, suggesting it should be evaluated further as potential (early) biomarker of infection." (PMID 38407673, 2024). "Also, cultured human keratinocytes produced IL-17C in response to infection with HSV-2." (PMID 32174926, 2020). "Thus, IL-17C would initiate a priming loop at the epithelial barrier that may have important consequences for establishment of infection and ensuing inflammatory responses, through the production, among others, of antimicrobial peptides." (PMID 30619119, 2018). "Following HSV-2 reactivation in sacral ganglia and infection of keratinocytes, infected cell protein 0 (ICP0) induces the expression of IL-17c, which stimulates neurite outgrowth in the human genital skin." (PMID 38275838, 2024). "Upon reactivation from human sacral ganglia and infection of keratinocytes in the genital skin, HSV-2 increases expression of interleukin 17c (IL-17c), a cytokine that induces neurite outgrowth." (PMID 38275838, 2024).
infection (continued). "Strong upregulation of IL17C and DEFB4, genes involved in epithelial intrinsic defenses (17, –, 19), suggests that upon sensing infection, epithelial cells mount a direct antimicrobial response in addition to producing chemokines to recruit other immune cells." (PMID 34006652, 2021). "The strongest responders to infection were cytokines CSF3, also called granulocyte colony-stimulating factor (G-CSF), and IL17C, and the antimicrobial peptide beta defensin-2 (DEFB4)." (PMID 34006652, 2021). "In addition, we recently showed that IL-17C, which plays a key role in regulating the innate immune function of epithelial cells and providing a link between inflammation control and maintenance of the mucosal barrier function during infection, was upregulated in the polyp tissue of CRSwNP." (PMID 27584662, 2016). "Interestingly, IL17C, whose role in UTI response is undefined, showed increased gene expression in both HBO lines and timepoints consistent with other infection response genes." (PMID 40766562, 2025). "There has not previously been a recognized role for IL-17C in infections with N. gonorrhoeae, nor in any inflammatory conditions of the upper reproductive tract." (PMID 38704381, 2024). "Following infection, IL-17C was not yet measurable in all donor samples at 8h but was measurable in all donor samples at 24h." (PMID 38704381, 2024). "An exception is il17c, which is upregulated 22-fold after infection with the NmB wild type strain in absence of U0126, but is upregulated 79-fold by the bacteria when the Erk1/2 signalling pathway is inhibited." (PMID 34863201, 2021). "Even though Il17c mRNA expression was upregulated 2 days after exposure to the fungus, the group did not observe a difference in clearance of the infection or gene expression profiles between mice lacking IL-17C or IL-17RE compared to a wildtype control group." (PMID 32174926, 2020). "HRV-16 (108 copies), which uses ICAM-1 as its receptor, led to measurable levels of IL-17C release from all 4 donors at 48 h post infection, but these were not significantly increased compared to control because of the wide range of individual values." (PMID 32232015, 2020). "Clinically, lack of signaling through the IL-17C/RE axis modeled with Il17re−/− mice lead to decreased mRNA levels of said molecules and failure to clear the infection." (PMID 32174926, 2020). "Within the non-leukocytic cell populations in the colon, Il17c induction was indeed limited to only the colonic epithelial cells since no mRNA upregulation Il17c was seen in colonic stromal cells after infection." (PMID 32174926, 2020). "Similar to the small intestinal tissues, only C83901 but not HB101 induced IL-17C mRNA expression in IPEC-J2 cells 4 h after infection." (PMID 31221216, 2019). "In addition, C83901 infection decreased occludin mRNA expression in IPEC-J2 cells at 4 h post stimulation, while IL-17C exerted the opposite effect." (PMID 31221216, 2019). "In contrast, IL-17C-/- and IL-17RE-/- mice completely cleared the infection by day 5, with no detectable fungal burden in the tongue." (PMID 25849644, 2015). "Thus, it is possible that IL-17C accelerates wound closure by supporting keratinocyte survival and the differentiation of wounds shortly after infection without affecting the clearance of S. aureus." (PMID 34576717, 2021). "The decreasing levels of serum IL-17C seen in LVLVs may suggest a role in early recruitment and differentiation of innate and adaptive modulators in response to HIV infection-i.e., prior to peak viral load, and subsequent downregulation in those who eventually go on to control infection." (PMID 33777023, 2021).